IGF1 (insulin like growth factor 1)
Diseases named in the same sentence as IGF1 in open-access papers (continued):
Sharing a sentence is not in itself a finding about the gene and the disease.
myocardial infarction (continued). "Furthermore, bone marrow mesenchymal stem cells overexpressing IGF-1 were reported to better resist apoptosis in myocardial infarction." (PMID 36970368, 2023). "Two female pigs (saline, 1; IGF-1, 1) had evidence of a myocardial infarction." (PMID 36602878, 2023). "IGF-1 levels were not independently associated with myocardial infarct size and dysfunction as assessed by MPS-SPECT imaging parameters at 6 weeks follow-up post-ACS." (PMID 34851758, 2021). "IGF‐1 could effectively improve cardiac function recovery after myocardial infarction (MI), and the protective effect of IGF‐1 on cell survival was mediated by activating various signalling pathways, including the PI3K/Akt signalling pathway." (PMID 33724692, 2021). "Cardiac IGF-1 deficiency is associated with an increased risk of cardiovascular ailments, whereas IGF-1 signaling activation protects the heart from detrimental metabolic stresses and myocardial infarction." (PMID 33466349, 2021). "Furthermore, the microencapsulated IGF-1 therapy reduces cardiac fibrosis in the porcine acute myocardial infarction model." (PMID 34244467, 2021). "We could not identify a statistically significant relationship between quartiles of IGF-1 and myocardial infarct size or LVEF." (PMID 34851758, 2021). "Therefore, IGF-1 levels have substantial associations with CVD; low concentrations are associated with myocardial infarction and cardiac failure." (PMID 33905470, 2020). "Certainly in settings where high levels of IGF1 secretion are desired, such as in the treatment of myocardial infarction, the use of MACS-derived ASC may be more beneficial compared to cultured-derived ASC." (PMID 32153389, 2019). "These in vitro data was the basis to pre-clinical test of the intracoronary injection of small amounts of IGF-1 and HGF (a single dose ranging from 0.5 to 2 μg HGF and 2 to 8 μg IGF-1) to pigs subjected to acute myocardial infarction (AMI) by transient coronary occlusion." (PMID 31275242, 2019). "After myocardial infarction and compared to ischemia-reperfusion injury, there was a significantly lower accumulation of c-Kit+ cells in the heart, consistent with the lower expression of endogenous IGF-1 and HGF in the myocardial infarction group." (PMID 22590612, 2012). "Moreover, intracoronary delivery of the MGF-24aa-E peptide elicits myocardial protection and improves hemodynamic function to a greater extent than mature IGF-1 following myocardial infarction in sheep." (PMID 23125840, 2012). "IGF-1 treatment enhanced circulating levels of angiogenic factors TGF-β and VEGF, while it reduced the enzymes associated with cardiac injury (CK-MB and LDH) in rats with induced myocardial infarction." (PMID 21651821, 2011). "Thus, IGF-1 has the potential to be a novel and efficient therapeutic strategy for myocardial infarction in humans for enhancing angiogenesis." (PMID 21651821, 2011). "Hence the present study was taken up with an objective to evaluate the effect of exogenous IGF-1 on circulating level of IL-8 and myocardial angiogenesis in experimentally-induced myocardial infarction in rats." (PMID 22272091, 2011). "The expression of IGF-1 has been shown to be increased in a variety of cardiac conditions, including acromegalic cardiomyopathy, chronically increased afterload or volume overload and acute myocardial infarction." (PMID 19818143, 2009). "As an example, diminished insulin-like growth factor 1 (IGF1) expression was found to protect senescent MSCs kept under conditions of hypoxia by means of an up-regulated autophagic flux, thus augmenting the survival of senescent MSCs after myocardial infarction transplantation." (PMID 32391362, 2020). "Thus, IGF-1 and cytokine IL-8 may be considered as a novel and efficient therapeutic strategy for myocardial infarction in humans by enhancing angiogenesis, leading to chronic improvement in cardiac function." (PMID 22272091, 2011).
myocardial infarction (continued). "Although the pathogenesis of acute myocardial infarction and SCM is different, IGF1's protective effect is clear in cardiomyocytes." (PMID 41555186, 2026). "Further, VEGF-A, IGF-1, HGF, and IL-8 gene expression was promoted at a high level by CXCL-6 in a myocardial infarction model." (PMID 37635970, 2023). "Lin and colleagues suggested that addition of IGF-1 would enhance viability, migration, and anti-apoptosis of MSC in myocardial infarction." (PMID 34876213, 2021). "Therefore, the present study aimed to investigate the association of IGF-1 serum levels at hospital admission with mortality and recurrent non-fatal myocardial infarctions in hyperglycemic non-insulin dependent ACS patients who participated in the BIOMArCS-2 trial and were followed for 5 years." (PMID 34851758, 2021). "At 4 weeks after myocardial infarction, VEGF, bFGF, HGF and IGF‐1 contents in the CSps group were 1.96, 3.12, 2.01 and 3.66 times those in the Control group, respectively (P < 0.05)." (PMID 29736937, 2018). "In the treatment of myocardial infarction, SAP carrying IGF-1 (SAP and IGF-1 were biotynilated and the streptavidin protein was used to create a molecular sandwich) was adopted to make cytokine play a long-term therapy role." (PMID 28773852, 2016). "Using an in vivo porcine myocardial infarction model, we analyzed the effectiveness for cardiac repair of heterologous paMSC previously transduced for HGF or IGF-1 overexpression (paMSC-mod)." (PMID 27423905, 2016). "After genetically modified MSC transplantation in myocardial infarction models, MSC survival and paracrine function of IGF-1 were enhanced significantly in vivo." (PMID 25429216, 2014). "The results of this study elaborate on our previous findings on the beneficial action of IGF-1 in the context of heart repair, where cardiac-specific IGF-1Ea propeptide expression improved recovery from myocardial infarction." (PMID 25056699, 2014). "After myocardial infarction IGF-1 improves cardiac function by stimulating contractility and promoting tissue remodeling, a decrease in IGF-1 expression affects myocardial function and myocyte regeneration." (PMID 25984322, 2013). "In this study we tested the hypothesis that mobilization of CPCs through locally delivered Hepatocyte Growth Factor and Insulin-Like Growth Factor-1 to heal chronic myocardial infarction (MI), lowers the proneness to arrhythmias." (PMID 21445273, 2011). "Adult male Sprague-Dawley rats were randomly divided into 10-days control, myocardial infarction, IGF-1 alone (2 μg/rat/day) and ISO+IGF-1 groups." (PMID 21651821, 2011). "transfected BMSCs with the IGF‐1 vector; they found that SFRP2 increased the activity and proliferation ability of BMSCs, inhibited apoptosis, and improved repair and regeneration ability after myocardial infarction." (PMID 40976879, 2025). "After myocardial infarction, CD117+ MPCs migrate to the area bordering the infarction through the activation of HGF-c-met, SDF1-CXCR4, and IGF1-IGFR signaling mechanisms, thus providing protection and repair of damaged myocardium presumably by secretion of bioactive compounds." (PMID 37958542, 2023). "IGF-1 overexpression in a subset of CD90+ CSCs was shown to activate IGF-1R signaling, promote stem cell survival, and protect surrounding cardiomyocytes from apoptosis after myocardial infarction." (PMID 36233084, 2022). "Additionally, priming MSCs with a cocktail of growth factors including FGF-2, IGF-1, and bone morphogenetic protein-2 (BMP-2) improved cardiac function in a rat model of myocardial infarction." (PMID 35008675, 2021). "Finally, direct IGF-1 + HGF administration was recently evaluated in a porcine model of chronic myocardial infarction (MI), in which growth factor delivery reduced pathological hypertrophy, led to formation of new small cardiomyocytes, and increased capillarization." (PMID 27423905, 2016).
myocardial infarction (continued). "In animal models of myocardial infarction, the intramyocardial injection of hepatocyte growth factor (HGF) and insulin-like growth factor 1 (IGF-1) activated the formation of cardiomyocytes and coronary vessels within the infarcted area through their binding to the receptors of the resident CSCs." (PMID 23407679, 2013). "Echocardiographic recordings and myocardial sampling for measurements of gene expressions of IGF-1, its receptor (IGF-1R), TGFβ and of cyclins A, B, D1, D2, D3 and E, were obtained in 8 dogs with a healed myocardial infarction, 8 dogs after 7 weeks of overpacing and in 7 healthy control dogs." (PMID 19818143, 2009). "Moreover, IGF-1 promotes BMSC migration and proliferation in myocardial infarction." (PMID 35272637, 2022). "Thus, pre-treated MSCs with insulin-like growth factor 1 (IGF-1) for 48 h markedly increased the CXCR4 expression in vitro, and a greater number of MSCs treated with IGF-1 engrafted and survived in the peri-infarcted area when the cells were transplanted in a rat model of myocardial infarction." (PMID 33796536, 2021). "We studied whether the in situ activation of eCSCs by insulin-like growth factor 1 (IGF-1) and hepatocyte growth factor (HGF) could be increased using a newly developed hydrogel in chronic myocardial infarction (MI)." (PMID 24395494, 2014). "Contrary to c-Kit, Isl1 was not up-regulated by pregnancy or myocardial infarction while ischemia-reperfusion injury induced not a global but a focal up-regulation in the outflow tract and also in the peri-ischemic region, correlating with the up-regulation of endogenous IGF-1." (PMID 22590612, 2012).
adenoma (97 papers, 1988 to 2026). A neoplasm arising from the epithelium. "The IGF1 axis has been extensively implicated in colorectal carcinogenesis, with elevated IGF1 levels associated with increased adenoma formation and malignant transformation." (PMID 41444654, 2025). "Following the selection process, we included 30 studies published between 1978 and 2020, which dealt with the following two issues: Twelve authors referred to systemic cardiovascular risk factors in patients with GH- and IGF-1-secreting adenoma." (PMID 36508085, 2023). "Early development of new adenoma (but not hyperplastic polyps) was shown to be associated with both elevated serum IGF-1 levels and previous adenoma during primary colonoscopy." (PMID 34208601, 2021). "In some prospective studies, inverse associations between baseline IGF-1 levels and future adenoma recurrence were reported, perhaps because of better health in the higher-level IGF-1 subgroups." (PMID 28620703, 2017). "Increased IGF-1 serum levels are also associated with a heightened risk of advanced adenomas." (PMID 39200386, 2024). "The importance of mixed GH and prolactin secreting adenomas in AIP-mutated patients is also highlighted by the experience of one case in the kindred whose profile suggests that mild IGF-1 excess might have developed over time." (PMID 32604740, 2020). "As confirmed by other studies, these patients, presenting with higher IGF-1 levels at diagnosis, generally exhibit a milder phenotype– i.e., smaller and less invasive adenomas– compared to those with a conventional GH response after OGTT." (PMID 39841390, 2025). "The levels of IGF-1, the ratio of IGF-1/IGFBP-3, and insulin have been found to be associated with adenomas and advanced adenomas." (PMID 39509387, 2024). "Its main goal is to achieve the normalization of GH and IGF-1 levels through a selective resection of the adenoma." (PMID 36335516, 2023). "The proliferation GH-secreting adenoma cells increases the blood circulating levels of GH and IGF-1." (PMID 35992136, 2022). "In brief, α-klotho stimulates GH secretion at the expense of ERK1/2 phosphorylation and blocks the inhibitory effect of IGF-1 on GH secretion in GH-secreting adenoma cultures." (PMID 35279809, 2022). "The relevant literature demonstrated that DG adenomas are mostly hypointense on T2W images and correlate with a smaller adenoma size, higher GH, and IGF-1 levels." (PMID 34307124, 2021). "Despite the significant effect of time (before vs. after treatment) on WBC, neutrophil counts, and NLR, SII values, we found that GH, IGF-1 concentrations, and adenoma MD showed statistically significant effects of group and time simultaneously." (PMID 34501445, 2021). "In particular, patients with an adenoma at first screening or an elevated serum IGF1 level above the maximum of the age-corrected normal range should be offered a screening every 3 years." (PMID 31293513, 2019). "Hypointense adenomas are smaller and less invasive than hyper- and isointense adenomas, but interestingly exhibit higher IGF-1 levels." (PMID 30232095, 2018). "The SRLs octreotide, lanreotide and pasireotide, as well as the dopamine agonist cabergoline, bind cognate receptors in the adenoma and suppress GH secretion; the GH antagonist pegvisomant blocks GH action in the periphery and blocks generation of IGF1." (PMID 30050156, 2018). "The IGF‐1 per cent reduction after 3 and 6 months of SSAs treatment was also significantly lower when we compared adenomas with low (score 1) and moderate/high (scores 2 and 3) SSTR2 expression (P = 0.001 and 0.003, respectively)." (PMID 29266696, 2018). "Other epidemiologic studies investigated IGF-1 and its primary binding protein IGFBP-3, which controls IGF-1 bioavailability, in relation to adenoma recurrence since IGF-1 promotes cell proliferation and inhibits apoptosis." (PMID 28620703, 2017).
adenoma (continued). "IGF-1 exerts anti-apoptotic effects and promotes epithelial proliferation, which is an important first step in the pathway to adenoma formation." (PMID 25329702, 2014). "From 215 cases with evaluable information on pituitary tumor size and IGF-1 levels, patients with macro-adenomas achieved IGF-1 normalization in 138 [77.5% of 178] instances and those with micro-adenomas in 33 [89.2% of 37] cases." (PMID 24039977, 2013). "After transsphenoidal adenoma resection, IGF-1 normalized, and medical therapy was discontinued." (PMID 40201458, 2025). "Although in our patient the GH and IGF-1 levels could be controlled as a result of transsphenoidal removal of the adenoma, the surgical damage produced hypopituitarism requiring hormone replacement therapy." (PMID 41567317, 2025). "Additionally, for ESS differential diagnosis, ectopic GH/IGF1 secreting adenoma in the bronchus and sphenoid sinus should be excluded." (PMID 38500594, 2024). "Surgical resection of the adenoma is the first-line approach for most patients, with normalization of age-adjusted IGF-1 concentrations and reduction of GH concentrations to < 1 μg/L (or < 0.4 μg/L with ultrasensitive assays) being the primary therapeutic target." (PMID 37543629, 2023). "Additionally, patients with GH/PRL-secreting adenomas had a higher rate of IGF-1 normalization (50%), and tumor shrinkage was detected in 62% (13/21) of patients." (PMID 35612842, 2022). "Moreover, miR-186-5p regulates IGF-1 expression and apoptosis in neuroblastoma cells and is also proposed as a screening biomarker in colorectal polyps and adenomas." (PMID 34187521, 2021). "Interestingly, >90% of patients who developed new adenomas had either neoplasia at the original colonoscopy or an elevated serum IGF1." (PMID 31293513, 2019). "In particular, adenomas with low E-cadherin expression was associated with decreased RORC expression following SA treatment and a blunted clinical response as demonstrated by attenuated IGF-1 and tumor size reduction." (PMID 23825587, 2013). "The highest level of agreement was reached for the lack of somatostatin receptors on adenoma and genetic predisposition as characteristic predicting resistance to fgSRLs (96% and 92%, respectively), and for IGF-1 levels being central for evaluating resistance (89% agreement)." (PMID 38809458, 2024). "Thus, we speculate that these cells are immature with a lower degree of differentiation and less specialized production of GH than the adenoma cells in GHPAs, leading to lower GH and IGF-1 at baseline in the mixed PA group than in the GHPA controls." (PMID 37324275, 2023). "Pegvisomant does not act directly on the adenoma, as the SSAs do; moreover, contrary to SSAs, it could increase GH secretion due to a loss of negative feedback from serum IGF-1." (PMID 32121432, 2020). "Moreover, those with pure SA were less likely to normalize IGF-1 than those with mixed adenomas." (PMID 24039977, 2013). "I consider radiotherapy as first-line treatment for any symptomatic patient with above normal IGF-1(≥1.5–2 ULN) with invasive and unresectable adenoma." (PMID 40575269, 2025). "We evaluated mRNA expression of IGFBP4, IGF1 and IGF1R in thyroid cancers, adenomas and hyperplastic nodules in comparison with their benign counterparts without observing any statistically significant differences." (PMID 34350538, 2022). "Moreover, it may be useful to differentiate GH-producing adenomas by imaging diagnosis in cases of pituitary apoplexy or severe visual dysfunction that require urgent or quasi-urgent surgery, because the IGF-1 blood test is often outsourced and generally has a long turn-around time." (PMID 33881731, 2021). "A strong immunohistochemical expression of IGF‐1 was observed in the lesions of both lung hyperplasia and NNK‐induced adenoma." (PMID 32083387, 2020). "Serum concentrations of adiponectin (pg/ml), IGF-1 (ng/ml), TNF-α (pg/ml), and leptin (pg/ml) were significantly higher in adenoma group." (PMID 29593647, 2018).